TEX54 (testis expressed 54)
Gene: Protein-coding gene on chromosome 11 (62,832,321 to 62,832,841, reverse strand). Ensembl gene ENSG00000283268.
Homologues: Orthologues: pig TEX54 (60% identical), mouse Tex54 (38% identical).